EZH2 (enhancer of zeste 2 polycomb repressive complex 2 subunit)
Diseases named in the same sentence as EZH2 in open-access papers (continued):
Sharing a sentence is not in itself a finding about the gene and the disease.
tumor (continued). "Inconsistent with the in vitro results, the tumor regression caused by EZH2 knockdown was partially rescued by MDA-5 inhibition." (PMID 35912007, 2022). "EZH2 catalyzes the H3K27me3 and histone marks, associated with tight chromatin and transcriptional repression, which lead to tumor progression." (PMID 36532284, 2022). "A recent study advises caution for this line of therapy by suggesting a tumor suppressive role of EZH2 using functional genomic gain- and loss-of-function studies in DMG mouse models." (PMID 36589742, 2022). "Multiple tumor driver genes that are associated with spermatogenesis pathway such as mTOR, EZH2, NF2, DCC and MLF1 had high enrichment score in the EGFR group." (PMID 35428753, 2022). "In this study, we demonstrate a tumor suppressor function for EZH2 using Ezh2 loss- and gain-of-function studies in H3WT DMG mouse models." (PMID 35395831, 2022). "A number of clinical trials have been performed to explore the role of EZH2 associated with ICIs in tumor immunotherapy, such as NCT02601950 and NCT04703192." (PMID 35911718, 2022). "Variants known to be associated with FL pathogenesis such as STAT6 p.D419 or EZH2 p.Y646 were observed in patient-matched cfDNA and tumor tissue samples." (PMID 35795062, 2022). "Genetic ablation of Ezh2 increased cell proliferation and tumor grade while expression of an Ezh2 gain-of-function mutation significantly reduced tumor incidence and increased tumor latency." (PMID 35395831, 2022). "To reveal the mechanism of EZH2 inhibition caused tumor regression in vivo, we analyzed the immune cell feature in the tumor microenvironment." (PMID 35912007, 2022). "FOXD2-AS1 inhibits cyclin-dependent kinase inhibitor 1A (CDKN1A) expression by recruiting enhancer of zeste 2 polycomb repressive complex 2 subunit (EZH2) and is linked to a poor prognosis in patients with OS and promotes tumor progression." (PMID 35659268, 2022). "This study integrated multiple prediction methods to assess the association between EZH2 expression and the abundance of infiltrating immune cells in PCa in order to better determine the impact of the tumor immune microenvironment." (PMID 36358967, 2022). "On univariate analysis, EZH2 expression was strongly associated with higher tumor grade, pT status, and tumor stage." (PMID 35740494, 2022). "Silencing of the lncRNA suppressed tumor growth in mice while in vitro CHiP assays confirmed that the knockdown inhibited EZH2 association with the CDKN1B promoter and limited the deposition of H3K27me3 without affecting EZH2 expression." (PMID 35788171, 2022). "For instance, reduction in EZH2 and H3K27me3 enrichment in the promoter of programmed cell death 4 is associated with impairments in cell proliferation and tumor growth." (PMID 35414117, 2022). "A ddPCR for detecting EZH2 mutations was set; interestingly, in a patient carrying two different mutations in different tumor sites, the analysis of ctDNA revealed both EZH2 genomic aberrations, so demonstrating the optimal representativeness of liquid biopsy." (PMID 35741115, 2022). "Mutation or over-expression of EZH2, a transferase involved in histone methylation, has also been linked to BRCA risk, and blocking EZH2 activity has been shown to slow tumor growth of BRCA10." (PMID 35739271, 2022). "The expression and activity of EZH2, one of the most well-known HMTs, have been associated with the tumor progression of various cancers." (PMID 35438143, 2022). "Functional interconnections among EZH2-mediated histone methylation and DNA methylation indicate the gene silencing involved in the loss of tumor suppression." (PMID 35216113, 2022). "In line with this—as reported in other tumor types—increased EZH2 expression was significantly associated with a higher tumor grade (p < 0.001)." (PMID 34638497, 2021).
tumor (continued). "In lymphoma, gain of function EZH2 mutations repress expression of tumor suppressor and late B cell genes, thus locking the B cell in a state of continuous proliferation at the germinal center stage of differentiation." (PMID 34001289, 2021). "Such RNA interference silencing of EZH2 has been utilised in a PC model and caused a decrease in tumour growth and the incidence of liver metastasis." (PMID 33673153, 2021). "EZH2 expression is also associated with the malignant features of the tumor and the poor prognosis of the patient." (PMID 34604069, 2021). "EZH2 is widely mutated in various cancer types and can act in both an oncogenic or tumor suppressive capacity." (PMID 34213777, 2021). "Although many EZH2 inhibitors were selectively designed for wild-type and mutant EZH2, most inhibitors just potentially inhibited the tumor-growth-bearing EZH2 mutations." (PMID 34503063, 2021). "Overexpression or activating mutations of EZH2 have been described in several malignancies, where they are usually associated with tumor aggressiveness, resistance to drug therapy and poor outcomes." (PMID 32920979, 2021). "Over the past decade, studies have established that EZH2 is overexpressed in malignancies and that its high expression is associated with tumor progression and poor prognosis." (PMID 34944658, 2021). "Similar to the current findings on SDC, in various cancers, the association between the expression of EZH2 and tumor progression has been indicated." (PMID 35186711, 2021). "GSK2816126 was highly active in inhibiting EZH2 mutated tumor growth with a maximum tolerated dose of 2400 mg by intravenous infusion and a dose-limiting toxicity of hepatic transaminitis (NCT02082977)." (PMID 34001246, 2021). "Loss of INI1 is common in epithelioid sarcoma and plays a crucial role in its sarcomatogenesis by impairing SWI/SNF function which causes aberrant PRC2 activity and tumor dependency on activating enhancer of zeste homolog 2 (EZH2) activity." (PMID 34349608, 2021). "In four patients with EZH2 mutations detected by ddPCR in ctDNA, the EZH2 VAFs fluctuated in accordance with tumour burden and in response to immunochemotherapy." (PMID 35844685, 2021). "No clinicopathologic factors (age, stage, or residual disease) were associated with differential EZH2 expression, cytolytic activity, or tumor-immune phenotypes." (PMID 34140011, 2021). "Surprisingly, the potency of temporal Treg Ezh2-deficiency was higher than systemic depletion of Tregs in controlling tumor progression, indicating a potential pro-inflammatory function of Ezh2-deficient Tregs." (PMID 33403469, 2021). "Defects in EZH2 have been described in multiple cancer types, and its overexpression is associated with a high proliferation rate, aggressive tumor progression and poor survival." (PMID 34815475, 2021). "EZH2 was demonstrated to be significantly associated with several immune checkpoints and tumour‐infiltrating lymphocytes." (PMID 33277782, 2021). "It is also considered to have a role in epigenetic modulation in tumor biology, as evidenced by the synthetic lethality of EZH2 inhibition in ARID1A‐mutated tumors." (PMID 33350171, 2021). "Overexpression of EZH2 is a common case in human cancers and is linked with tumor progression and poor prognosis." (PMID 34604069, 2021). "Inhibitors targeting EZH2 also induce the re-expression of tumor suppressors associated with enhanced patient survival." (PMID 34771678, 2021). "It is of interest to delineate the associations between EZH2, tumor immune phenotypes, and prognosis in future studies." (PMID 34140011, 2021).
tumor (continued). "The activity of both enzymes increases in hypoxic tumour microenvironments and is linked to the silencing of tumour suppressor genes and survival in breast cancer, while EZH2 transcription is enhanced by HIF-1α to promote more aggressive phenotypes." (PMID 33669182, 2021). "An increase in EZH2 and H3K27me3 levels has been reported to be associated with aggressive tumor phenotypes and unfavorable prognosis." (PMID 34725436, 2021). "As a tumor suppressor, loss of EZH2 accelerates Ras-driven neoplastic processes and can amplify Akt and ERK activation." (PMID 34947882, 2021). "Overexpression of EZH2 promoted an undifferentiated NB tumor phenotype and was associated with poor clinical outcome, while its pharmacological inhibition (tazemetostat) resulted in reduction of proliferation." (PMID 33404859, 2021). "Overexpression of EZH2 was reported also in OS where it is associated with a highly aggressive tumor phenotype and poorer prognosis." (PMID 33811471, 2021). "Chemotherapy activated the EZH2/STAT3 pathway in tumor cells, which caused an increase in miR-378a-3p and miR-378d levels in cells and exosomes." (PMID 33823894, 2021). "EZH2 is associated with a high proliferation rate, aggressive tumor subtypes, and poor outcome of patients with cancer." (PMID 33966039, 2021). "Recall that the EZH2+CD8+ T cell population highly associates with the enhanced anti-tumor response, miR-101 and miR-26a inhibit the expression of EZH2 in CD8+ T cells." (PMID 35087832, 2021). "In patients with MDS or MDS/MPN, recurrent loss-of-function EZH2 mutations are associated with a poor prognosis, and EZH2 is considered by many to act as a bona fide tumor suppressor gene." (PMID 33845873, 2021). "The association of EZH2 H-score with response to therapy and overall survival was evaluated by tumor features." (PMID 34140011, 2021). "Many cancer indications overexpress EZH2, including prostate, breast, and bladder, and gain-of-function mutations suggest that cancer cells utilize this pathway to promote tumor progression." (PMID 34925340, 2021). "Aberrant expression of EZH2 has been linked to cancer development and progression in several tumor types, while available data suggest a link with EMT phenotypic changes." (PMID 34199763, 2021). "A 2010 study showed that high expression levels of EZH2 in PC were associated with increased node positivity and a larger tumour size; EZH2 expression levels were also shown to relate to the degree of dysplasia in IPMNs." (PMID 33673153, 2021). "Taken together, these results highlight the association between proximal tumor-gained promoters with EZH2 and SUZ12 occupancies, which potentially affects the expressions of developmental regulatory genes such as EPCAM." (PMID 33916417, 2021). "In summary, in this study, we explored the expression of EZH2 mutation, the gene variation of EZH2, and the relationship between the prognosis potential of the EZH2 gene and the whole tumor by using the public database." (PMID 34381492, 2021). "The search for associations between EZH2 expression and tumor phenotype was limited to the largest subset of 1053 analyzable clear cell RCC." (PMID 32303902, 2021). "ARID1A alterations or expression loss leads to the advantage of EZH2 function and result in the excessive proliferation of tumor cells." (PMID 34715776, 2021). "N-Myc can also directly interact with EZH2, and overexpression of EZH2 promotes an undifferentiated NB tumour phenotype associated with poor clinical outcomes." (PMID 34884690, 2021). "Consistent with our observation that USP7 coordinated with the PRC2 complex is linked to downregulation of FOXO1, we showed that the expression level of FOXO1 is decreased and negatively associated with those of USP7 and EZH2 in various tumor tissue samples." (PMID 33849069, 2021).
tumor (continued). "The tight relationship of EZH2 expression and CD8+ cell counts in RCC is consistent with models suggesting that EZH2 overexpression can be caused by high lymphocyte content in certain tumor types." (PMID 32303902, 2021). "EZH2 variant allele frequencies changed in parallel with the volume of metabolically active tumor sites observed on 18F-fluorodeoxyglucose positron emission tomography combined with computer tomography (PET-CT) scans." (PMID 32668764, 2020). "Previous studies have reported that MEG3 was associated with EZH2, and that EZH2 was a tumor target, which acted as an oncogene in NB." (PMID 33061817, 2020). "Overexpression of EZH2 has been shown to be associated with higher tumor cell proliferation, advanced stage, and predicted poorer overall survival." (PMID 32098335, 2020). "Several therapeutic approaches have been explored for BAP1-deficient tumours, including chemotherapeutic drugs (e.g. gemcitabine), radiotherapy and small molecule inhibitors (e.g. EZH2 inhibitors) with limited success." (PMID 33240524, 2020). "In cancer, DNA methyltransferases such as DNMT1 and histone methyltransferases such as EZH2 are associated with low tumor-infiltrating CD8+ T cells and patient outcomes." (PMID 32708698, 2020). "As a crucial epigenetic regulator of gene expression, EZH2 is associated with multiple aspects of many carcinomas, such as tumor initiation, invasiveness, metastasis, angiogenesis, and chemoresistance." (PMID 32754259, 2020). "Disrupting the ability of pRB to recruit EZH2 in mouse models results in cancer susceptibility, suggesting a role for pRB-EZH2 in tumor suppression." (PMID 33003565, 2020). "In a mice model, anti-CTLA4 MoAbs or IL-2 led in T-cells and TNF-a accumulation and Ezh2 expression, which caused immunogenicity loss of tumor, lower antigen expression and resistance to immunotherapy." (PMID 32344837, 2020). "Accordingly, elevated EZH2 expression was also associated with adverse prognosis in several other tumor entities, such as breast, cervical, larynx and colorectal cancers." (PMID 33230143, 2020). "Overexpression of EZH2 in tumor cells has been implicated in tumor growth, and has inverse correlation with treatment outcome in various cancer types." (PMID 32850364, 2020). "After the combined treatment, it was found that two EZH2 target genes were upregulated, namely the tumor suppressor gene RASSF5 (ras association domain family member 5) and ITGB2 (integrin subunit Beta 2), which is associated with anti-tumor immunity." (PMID 32751889, 2020). "To further investigate the mechanism underlying tumor suppression, we analyzed xenograft tumor sections using Immunohistochemistry to verify EZH2 protein expression level." (PMID 33276757, 2020). "Elevated expression of EZH2 is found to be associated with poor clinical prognosis and tumor invasiveness in various types of cancers." (PMID 32754274, 2020). "Investigation of relationships between ALN status and investigated parameters showed that ALN metastases were closely linked to tumor stage (p=0.012), clinical stage (p=0.019) and expression of EZH2 (p=0.003)." (PMID 33235571, 2020). "Mutant forms and abnormal expression patterns of EZH2 have beendetected in several cancers and are frequently associated with tumor progression andpoor prognosis." (PMID 32453339, 2020). "22.0% of GCB and 1.7% of ABC DLBCL exhibited gain-of-function mutations in EZH2 that mediated epigenetic modification and led to tumor survival." (PMID 33317571, 2020). "BKM120-induced reduction in the levels of CHAF1A and Caspase 3, pATR, DRIP130, EZH2, and Ki67 was associated with more effective tumor growth inhibition, while increased phosphorylation of Aurora kinases was associated with resistance." (PMID 33371187, 2020).
tumor (continued). "Although the frequency of overexpression and gain-of-function mutations suggests an oncogenic role for EZH2, there is also evidence suggesting that EZH2 acts as a tumor suppressor in some cancers." (PMID 33003334, 2020). "At the post-transcriptional level, loss of miR-26a, miR-101, let-7, and miR-138 increases EZH2 level in tumor PC." (PMID 33126754, 2020). "EZH2 is one of the known methyl transferases producing H3K27me3 which is most often regulated by transcription factors, tumor suppressor microRNA and cancer-associated non-coding RNA24." (PMID 32483123, 2020). "It is known that glutamine metabolism increases in tumors with EZH2 inactivated mutations, and the activated energy metabolism promotes tumor progression." (PMID 32448308, 2020). "Recently, various oncogenic properties have been linked to EZH2, including impaired cellular differentiation, enhanced proliferation, and tumor growth." (PMID 32635336, 2020). "This tumor-associated lncRNA was reported to function as an oncogene by downregulating the expression of PDCD4 through recruiting EZH2 and altering trimethylation levels of H3K27 in ESCC cells." (PMID 32194853, 2020). "In terms of EZH2, mutation or overexpression of EZH2 is known to help cancerous cells divide and proliferate by inhibiting genes responsible for suppressing tumor development." (PMID 33291558, 2020). "The frequency (~5–10%) of inactivating EZH2 mutations found in MF suggests loss of EZH2-mediated methylation contributes to neoplastic disease." (PMID 33329600, 2020). "Of note, however, our data suggest that loss of Ezh2 mediates its tumor-suppressive effects predominantly through alterations of H3K27me3 at promoters rather than enhancers." (PMID 30890554, 2019). "In muscle-invasive bladder cancer (MIBC), KDM6A and members of the SWI/SNF family members are frequently mutated, while EZH2 is overexpressed in tumors compared to adjacent non-tumor areas." (PMID 30692641, 2019). "Taken all together, these data, obtained in large numbers of primary patient samples, corroborate our experimental findings on the tumor-suppressive role of EZH2 during AML induction and further implicate mutation of EZH2 as a poor prognostic factor in AML." (PMID 30890554, 2019). "In MDS and AML, both overexpression and loss-of-function mutations of EZH2 gene suggest that it can function as an oncogene or as a tumor suppressor gene, respectively." (PMID 31886200, 2019). "This leads to the conclusion that a reduction or complete loss of EZH2 expression resulting in a stop of proliferation represents a promoting factor associated with the dissemination of tumor cells and the formation of metastases." (PMID 31317325, 2019). "Further mechanistic research showed that the expression level of the tumor suppressor gene p16INK4a is downregulated in SMARCB1/SNF5-deficient tumor cells and increased in EZH2-deficient cells." (PMID 31590683, 2019). "It was also found that SMARCB1/SNF5-deficient tumor cells are highly sensitive to EZH2 inhibitors, which significantly inhibit cell proliferation and increase apoptosis." (PMID 31590683, 2019). "Our findings showed that high EZH2 expression level was associated with tumor cell lines and poorer prognosis and in vitro experiments testified that EZH2 promoted cell proliferation, migration, and invasion in ccRCC." (PMID 30755832, 2019). "While investigating the association of the identified EZH2 target genes, we found two of them are good for cancer as oncogenes and the function of other four suggests them to serve as tumor suppressor genes." (PMID 30760814, 2019). "Several reports have indicated that EZH2 expression in NSCLC is associated with aggressive tumor phenotypes, advanced stage and poor survival." (PMID 31042721, 2019). "Here, the software confirmed the results of the manual analysis demonstrating a remarkable loss of EZH2 and the corresponding repressive H3K27me3 code expression at the tumor invasion front compared to the tumor center." (PMID 31317325, 2019).